TEAD2 (TEA domain transcription factor 2)
Description:
Transcription factor which plays a key role in the Hippo signaling pathway, a pathway involved in organ size control and tumor suppression by restricting proliferation and promoting apoptosis. The core of this pathway is composed of a kinase cascade wherein MST1/MST2, in complex with its regulatory protein SAV1, phosphorylates and activates LATS1/2 in complex with its regulatory protein MOB1, which in turn phosphorylates and inactivates YAP1 oncoprotein and WWTR1/TAZ. Acts by mediating gene expression of YAP1 and WWTR1/TAZ, thereby regulating cell proliferation, migration and epithelial mesenchymal transition (EMT) induction. Binds to the SPH and GT-IIC 'enhansons' (5'-GTGGAATGT-3'). May be involved in the gene regulation of neural development. Binds to the M-CAT motif.
Synonyms: TEAD-2; TEF4; TEF-4; ETF
Tractability: Small molecule: a structure with a bound ligand is known; a high-quality ligand is known. PROTAC: ubiquitination databases record sites on it; a small molecule that binds it is known.
Target class: Transcription factor
Chemical probes: GNE-7883 (high quality), VT104 (high quality)
Gene: Protein-coding gene on chromosome 19 (49,340,585 to 49,362,729, reverse strand). Ensembl gene ENSG00000074219.
Subcellular location: Nucleus
Subcellular location (Human Protein Atlas): Nucleoplasm
Pathways (Reactome):
Gene expression (Transcription): RUNX3 regulates YAP1-mediated transcription; YAP1- and WWTR1 (TAZ)-stimulated gene expression
Developmental Biology: Formation of axial mesoderm
Immune System: Regulation of PD-L1(CD274) transcription
Gene Ontology:
Molecular function: disordered domain specific binding; DNA-binding transcription factor activity; protein binding; sequence-specific double-stranded DNA binding; transcription coactivator binding; DNA-binding transcription factor activity, RNA polymerase II-specific; RNA polymerase II cis-regulatory region sequence-specific DNA binding; DNA binding
Biological process: hippo signaling; positive regulation of DNA-templated transcription; protein-containing complex assembly; embryonic organ development; regulation of DNA-templated transcription; regulation of transcription by RNA polymerase II; mesenchyme development; nervous system development
Cellular component: nucleoplasm; TEAD-YAP complex; chromatin; nucleus; transcription regulator complex
Genetic constraint (gnomAD): Loss-of-function variants: 51 observed, 62.22 expected, observed/expected ratio (o/e) 0.82, 90% interval 0.65 to 1.03. The upper end of that interval is the gene's LOEUF score, 1.03, which puts it in group 4 of 6, group 1 being the genes least tolerant of losing a copy. Missense variants: 509 observed, 610.65 expected, observed/expected ratio (o/e) 0.83, 90% interval 0.77 to 0.9. Synonymous variants: 244 observed, 253.26 expected, observed/expected ratio (o/e) 0.96, 90% interval 0.87 to 1.07.
Homologues: Orthologues: chimpanzee TEAD2 (99% identical), macaque TEAD2 (99% identical), dog TEAD2 (98% identical), guinea pig TEAD2 (98% identical), pig TEAD2 (97% identical), rat Tead2 (93% identical), mouse Tead2 (92% identical), rabbit TEAD2 (67% identical). Paralogues in human: TEAD1 (63% identical), TEAD3 (62% identical), TEAD4 (62% identical).
Diseases named in the same sentence as TEAD2 in open-access papers:
TEAD2 is named in the same sentence as 41 diseases in open-access papers, as found by Europe PMC text mining. Sharing a sentence is not in itself a finding about the gene and the disease. The quoted sentences say what the papers report.
breast carcinoma (8 papers, 2018 to 2024). "Depletion of TEAD2 suppresses the ability of YAP to induce invasion in melanoma cells while is overexpressed in trastuzumab resistant breast cancer cells." (PMID 38755629, 2024). "Previous studies showed that the expression of TEAD2 was enriched in the nucleus and directed a predominant nuclear localization of YAP via the formation of TEAD2-YAP complex in the process of epithelial-mesenchymal transition of breast cancer cells." (PMID 35739490, 2022). "YAP1 dephosphorylation and TEAD2 overexpression were detected as significant alterations in the Hippo pathway in trastuzumab-resistant breast cancer." (PMID 32365528, 2020). "A recent report has shown that TGF-β-mediated Tead2 upregulation could contribute to EMT in mouse breast cancer cells." (PMID 34789779, 2021). "Among the genes regulated by Bcl-2 in both melanoma and breast carcinoma models we identified CTGF, CCND3, TEAD2, FST, MYC and TP73." (PMID 38755629, 2024). "Consistent with the results from breast cancer patient-derived CTCs, we observed downregulation of focal adhesion, cell–matrix adhesion, and ECM components as well as suppression of TEAD2 in CTC clusters relative to their primary tumor counterparts." (PMID 36991428, 2023). "TEAD2, a transcriptional enhancer factor, contributes to EMT in breast cancer and pancreatic adenocarcinoma (PDAC) by directing its co-factor YAP1 to the nucleus." (PMID 31143705, 2019).
glioma (5 papers, 2016 to 2021). A benign or malignant brain and spinal cord tumor that arises from glial cells (astrocytes, oligodendrocytes, ependymal cells). "Functional validation with CRISPR-Cas9-induced mutations in novel genes Tead2, Spred1, and Nav3 demonstrates heightened EGFRvIII-glioma cell proliferation." (PMID 32727536, 2020). "To further explore whether the Hippo pathway could influence epithelial-mesenchymal transition (EMT) in glioma cell lines, we first designed siRNA to respectively downregulate the expression of YAP1 and TEAD2, two important downstream factors of the Hippo pathway." (PMID 28548934, 2017). "They found that TEAD2–4 were significantly correlated with LGG survival, but the detailed information of the relationship between TEADs and glioma patients’ outcome was not clearly elaborated." (PMID 33889755, 2021). "In glioma, only TEAD2 has been reported to bind with TAZ to regulate transcription of a majority of mesenchymal genes, while TEAD4 has not been reported to bind with TAZ in glioma cell up to now." (PMID 27764783, 2016).
gastric cancer (2 papers, 2020 to 2025). A primary or metastatic malignant neoplasm involving the stomach. "To further confirm the role of YAP1 in the regulation of AGK in gastric cancer cells, we associated AGK expression with other YAP1‐related proteins in gastric cancer tissue samples and found that AGK expression was also associated with the expression of TEAD1, TEAD2 and TEAD4." (PMID 32827244, 2020). "Meanwhile, miRNA-125a was reported to have oncogenic potential, which may promote the progression and invasion of gastric cancer through the regulation of EphA2, TAZ, and TEAD2 and myeloma progression through a reduction in DIS3 expression level." (PMID 40282476, 2025).
glioblastoma (2 papers, 2017 to 2021). The most malignant astrocytic tumor (WHO grade IV). "More importantly, we testify that IKBKE accelerates EMT of glioblastoma cells via IKBKE-dependent YAP1/TEAD2 activation." (PMID 28548934, 2017). "Additionally, we respectively overexpress YAP1 and TEAD2 in glioblastoma cell lines transfected with IKBKE-shRNA." (PMID 28548934, 2017). "These researches and our experimental data provide the theoretical basis that IKBKE promotes glioblastoma growth and EMT through IKBKE-dependent YAP1/TEAD2 activation." (PMID 28548934, 2017).
intrahepatic cholangiocarcinoma (2 papers, 2023 to 2024). A carcinoma that arises from the intrahepatic bile duct epithelium in any site of the intrahepatic biliary tree. "Nevertheless, a tumor suppressor role of FTO has been described in intrahepatic cholangiocarcinoma (ICC) by controlling different pathways, including EGFR, and by decreasing the stability of the oncogene TEAD2." (PMID 37369946, 2023). "In RCC, FTO promotes angiogenesis by inhibiting von Hippel-Lindau tumor suppressor (VHL) expression, whereas in intrahepatic cholangiocarcinoma (ICC), FTO suppresses angiogenesis by inducing TEA domain transcription factor 2 (TEAD2) expression." (PMID 39098905, 2024).
liver cancer (2 papers, 2020 to 2022). An epithelial or non-epithelial malignant neoplasm that arises from the liver. "In terms of the contribution of TEAD-2 to tumorigenesis, the APA modification of TEAD-2 may be functionally related to liver cancer development, suggesting that this gene may be a potential biomarker for the identification of a particular tumor type." (PMID 32626751, 2020).
liver fibrosis (2 papers, 2022 to 2025). "Tanshinones, including tanshinone IIA, tanshinone I and dihydrotanshinone I, have been reported to treat liver fibrosis by inhibiting the activation of HSCs, regulating PI3K/Akt signaling pathways, disrupting the YAP /TEAD2 complex, and stimulating autophagy." (PMID 35517817, 2022).
myeloma (2 papers, 2021 to 2025). "Some of these TFs were specifically downregulated in MSCs of active myeloma (RUNX2 and TEAD2), others were already downregulated in precursor myeloma stages (HOXC9 and CEBPD), whereas other TFs, including HOXA2 and ATF3, did not change their expression in any myeloma stages." (PMID 33462210, 2021).
Burkitt lymphoma (1 paper, 2021). A rare form of malignant mature B-cell non-Hodgkin lymphoma. "In support of our results here, results presented in the Human Protein Atlas database indicate that RNA transcripts of YAP, TAZ, and the four TEAD family members (TEAD1, TEAD2, TEAD3, and TEAD4) are not detected in the EBV-infected Burkitt lymphoma cell line, Daudi." (PMID 34339458, 2021).
colorectal cancer (1 paper, 2023). A primary or metastatic malignant neoplasm that affects the colon or rectum. "PHF5A could also promote colorectal cancer progression by alternative splicing of TEAD2." (PMID 37434235, 2023).
colorectal tumor (1 paper, 2023). "Stimulation of the YAP signaling pathway leading to aberrant regulation of alternative splicing of TEAD2 gene exon 2 to its full-length isoform (TEAD2-L) was described as the suggested tumorigenesis mechanism with ultimate enhanced proliferation, metastasis, and progression of colorectal tumor." (PMID 37483794, 2023).
dilated cardiomyopathies (1 paper, 2024). "In addition to known associations, our analysis also identified novel regulators, including the identification of TFs FPM315 and OVOL2, which are implicated in dilated cardiomyopathies, and TEAD1 and TEAD2 in both dilated and ischemic cardiomyopathies." (PMID 38673810, 2024).
hepatoblastoma (1 paper, 2019). Hepatoblastoma (HB) is a malignant hepatic tumor and is the most common pediatric liver cancer. "The blockade of TEAD2 function was associated with a decrease in development of hepatoblastoma in mice and reduction in cellular proliferation in hepatoblastoma cell lines." (PMID 31511432, 2019). "On the other hand, activation of TEAD2 DNA-binding domain (by fusing with transcriptional activation domain) synergized with β-catenin and led to the development of hepatoblastoma in mice." (PMID 31511432, 2019).
hepatocellular carcinoma (1 paper, 2022). A malignant tumor that arises from hepatocytes. "Besides, the expression of TEAD2 is associated with a poor prognosis in hepatocellular carcinoma patients, which can be considered as a therapeutic target of hepatocellular carcinoma." (PMID 35739490, 2022).
intestinal tumours (1 paper, 2021). "We next sought to directly test whether TEAD1/4 and TEAD2 are induced upon activation of Wnt signalling in ApcMin mutant intestinal tumours." (PMID 33950519, 2021).
lung carcinoma (1 paper, 2024). "Serum FST levels was found higher in lung cancer patients respect to healthy subjects and in patients with lung benign disease, while TEAD2 targeting was responsible of cisplatin sensitization in NSCLC." (PMID 38755629, 2024). "In our study we also found the downregulation of both TEAD2 and FST genes, in lung cancer cells after Bcl-2 silencing." (PMID 38755629, 2024).
malignant glioma (1 paper, 2017). A grade III or grade IV glioma arising from the central nervous system. "We also testified that YAP1 and TEAD2 promoted epithelial–mesenchymal transition (EMT) in malignant glioma." (PMID 28548934, 2017). "So we assumed that IKBKE promoted malignant glioma growth and EMT via enhancing the expression of YAP1 and TEAD2." (PMID 28548934, 2017).
neuroblastoma (1 paper, 2020). Neuroblastoma (NB) is the most common solid, extracranial childhood tumor. "We expressed Tead1-flag or Tead2-flag with either HA-tagged Yap1 or HA-tagged Taz in neuroblastoma cells (N2A) and performed co-immunoprecipitation experiments." (PMID 32170161, 2020).
non-small cell lung carcinoma (1 paper, 2024). A group of at least three distinct histological types of lung cancer, including non-small cell squamous cell carcinoma, adenocarcinoma, and large cell carcinoma. "Another study showed that, MicroRNA-608 could sensitize cisplatin therapy of non-small cell lung cancer cells by targeting TEAD2, and overexpression of TEAD2 reduced miR-608-induced apoptosis of A549 cells under cisplatin." (PMID 39430767, 2024).
ovarian carcinoma (1 paper, 2014). A malignant neoplasm originating from the surface ovarian epithelium. "YAP and TEAD family members, except for TEAD2, were all expressed at significantly higher levels by OCICs than by differentiated ovarian cancer cells." (PMID 25369529, 2014).
pancreatic cancer (1 paper, 2022). "Consistent with our findings, the role of YAP/TEAD2 complex in driving MCM6 expression at the transcriptional level was depicted in pancreatic cancer." (PMID 36185598, 2022).
renal fibrosis (1 paper, 2025). A final common manifestation of a wide variety of chronic kidney diseases characterized by glomerulosclerosis and tubulointerstitial fibrosis. "Collectively, these results suggest that PKM2 regulates TEAD2 expression and may contribute to renal fibrosis progression by modulating CCN2 expression in tubular epithelial cells through the formation of transcriptional complexes with YAP1 and β-catenin." (PMID 41380965, 2025).
Sveinsson Chorioretinal Atrophy (1 paper, 2023). "Diseases associated with TEAD2 include Sveinsson Chorioretinal Atrophy and Multiple Acyl-CoA Dehydrogenase Deficiency." (PMID 36641432, 2023).
vascular tumors (1 paper, 2024). "Expression of a TEAD2 dominant-negative protein also inhibited the ability of TAZ::CAMTA1 to induce the formation of EHE-like vascular tumors and lethality in mice." (PMID 40491864, 2024). "For instance, we showed that genetic inactivation of the TAZ::CAMTA1–TEAD signaling axis by overexpression of a dominant-negative TEAD2 could completely prevent the formation of TAZ::CAMTA1-dependent EHE-like vascular tumors in mice." (PMID 40491864, 2024).
tumor (24 papers, 2015 to 2026). "Notably, additional molecular events such as mutations in TMEM140 and TEAD2 were found to be shared in all the five geographically distinct tumor specimens obtained from the same individual." (PMID 29510530, 2018). "TEAD2 has been found to be relevant to tumor suppression by restricting proliferation and promoting apoptosis through the Hippo signaling pathway." (PMID 36467501, 2022). "TEAD2 is significantly overexpressed in tumor samples with lower overall survival rate in TCGA Liver Hepatocellular Carcinoma database." (PMID 35602596, 2022). "Induction of TEAD2-DN by doxycycline administration in vivo induced a significant tumor growth inhibition (TGI) of 44% (p < 0,0001) when doxycycline was administered right after tumor cell implantation." (PMID 35689194, 2022). "The effect of YAP1 downregulation on tumor growth was first tested in vitro using a genetic approach based on a TEAD dominant-negative (TEAD2-DN) construct." (PMID 35689194, 2022). "Furthermore, YAP1 promoted tumor stemness maintenance partly by acting as a transcriptional coactivator to promote TEAD2-induced SOX2 expression." (PMID 35864972, 2022). "Together with TMEM140, TEAD2, OR1J2, and GRIN2B, many other genes were commonly mutated across the tumor samples, however the recurrence always occurred when examining multiple metastatic samples of the same individual (T07–11 or T04–05 corresponding respectively to patients P06 and P04)." (PMID 29510530, 2018). "Then, we further discovered that IKBKE increased Yes-associated protein 1 (YAP1) and TEA domain family member 2 (TEAD2), two important Hippo pathway downstream factors, to induce an epithelial–mesenchymal transition (EMT), thus contributing to tumour invasion and metastasis." (PMID 28548934, 2017). "In MDA-MB-231 cells, all the tested genes were significantly downregulated in si-Bcl-2 condition, except for TEAD4, while only for TEAD2 transcript a significant modulation was observed in Bcl-2 silenced H460 cells, suggesting that Bcl-2 can affect Hippo pathway depending on the tumor histotype." (PMID 38755629, 2024). "This comparison showed a very high degree of overlap in the percentage of target loci where VGLL1 bound compared to those targets previously identified for TEAD1, TEAD2, TEAD3, and TEAD4 (p < 10e-370 for all 3 tumor cell lines)." (PMID 38912065, 2024). "Some TFs were specific for individual cell lines, others were shared between two cell lines, and a total of eight TFs were shared amongst all three tumor types, including TEAD1, TEAD2, TEAD3, TEAD4, GRHL2, RUNX2, AP1, and GATA6." (PMID 38912065, 2024). "TEAD2 and 4 were significantly upregulated in HNSCC samples as compared to their non-tumor counterparts, while TEAD1 and TEAD3 were markedly downregulated in cancerous samples relative to non-tumor samples." (PMID 30459528, 2018). "Additionally, genes typically involved with tumor growth and persistence were downregulated with the addition of ARG2i/COX2i/NOS2i to STING agonism (e.g., Ar, Tgfb3, Tead2, Pik3r2, Jun)." (PMID 38312842, 2024). "Intriguingly, VGLL4, but not YAP/TAZ, is correlated with TEAD2 in tumor samples, suggesting TEAD2 modulates HCC progression in a YAP-independent manner." (PMID 35602596, 2022). "TEAD2, another predicted gene with an APA-modified pattern, may also have different APA modification patterns in various tumor types." (PMID 32626751, 2020).
tumor (continued). "Additionally, YAP1 and TEAD2, two vital Hippo pathway downstream transcription factors, obviously decreased in IKBKE-silenced tumour cells, suggesting that the reversed EMT process caused by IKBKE downregulation was likely regulated by the Hippo pathway." (PMID 28548934, 2017). "The survival of tumor cells in this model in the absence of Kras is mediated by the upregulation of the transcriptional coactivator Yap1, a downstream mediator of the Hippo signaling cascade, and Tead2, forming Yap1/Tead2 complexes coordinating downstream gene expression." (PMID 34888306, 2021). "Furthermore, TEAD2, a TF that plays a key role in the Hippo signalling pathway by interacting with YAP1, was predicted to bind and regulate four lincRNAs (LINC00261, RP11-161M6.2, GMDS-AS1, MIRLET7BHG), three of them showing the strongest decrease in basal-like tumours." (PMID 32727085, 2020).